IGF1R (insulin like growth factor 1 receptor)
Diseases named in the same sentence as IGF1R in open-access papers (continued):
Sharing a sentence is not in itself a finding about the gene and the disease.
melanoma (continued). "Western blot analysis confirmed the overexpression of IGF-1R in malignant melanoma B16F10 cells." (PMID 39920417, 2025). "A direct regulation of IGF1R by miR-30a-5p and miR-376a was shown in melanoma cells." (PMID 38539461, 2024). "IGF-1R plays a critical role in tumor progression and has been extensively documented in numerous cancer types, including breast, ovary, prostate, colorectal, pancreatic, melanoma, and thyroid." (PMID 39638246, 2024). "In BRAF mutant melanoma resistant to BRAFi and MEKi, IGF1R activation induces ERK5 phosphorylation." (PMID 37420093, 2023). "In the case of BRAF inhibitor resistance in melanoma, for example, this speciation event may occur through activation of RTKs like IGF-1R or through engagement of the PI3K pathway via PTEN inactivation." (PMID 36853375, 2023). "Additionally, the insulin-like growth factor-1 (IGF-1R) can contribute to BRAF resistance to targeted therapies in melanoma." (PMID 37174072, 2023). "Knowledge of the status of the PTEN/ATF6/Entpd5/IGF1R axis may prove to be valuable in the design of novel preventive and interventive therapeutic strategies in melanoma." (PMID 36824269, 2023). "Similarly, IGF1R/Insulin Receptor (IR) expression increased in D/T combination-resistant melanoma cells in correlation with poor patient survival." (PMID 37834284, 2023). "The LINC01291/miR-625-5p/IGF-1R signaling pathway may represent a novel therapeutic target for melanoma therapy." (PMID 33674778, 2022). "A series of experiments were designed to evaluate whether sequestering miR-625-5p is necessary for the regulatory activities of LINC01291 on IGF-1R in melanoma cells." (PMID 33674778, 2022). "Functional rescue experiments were conducted to determine whether LINC01291 affects tumor processes in melanoma cells by decoying miR-625-5p and increasing IGF-1R." (PMID 33674778, 2022). "Additionally, IGF-1R expression in melanoma tissues was measured via qRT-PCR, which confirmed that IGF-1R was highly expressed and inversely associated with LINC01291 expression in melanoma tissues (r = −0.6640, P < 0.0001)." (PMID 33674778, 2022). "Therefore, our results corroborate that LINC01291 exhibits its tumor-promoting effects during melanoma progression by targeting the miR-625-5p/IGF-1R axis." (PMID 33674778, 2022). "These authors also established that insulin-like growth factor receptor 1 (IGF-1R) was upregulated (by stabilization) and ERK1/2i-resistant melanoma cells were dependent on IGF1-R activity (using the IGF1-R inhibitor, linsitinib) for cell proliferation in vitro, in spheroids and in xenograft models." (PMID 35903549, 2022). "Rescue experiments revealed that the roles induced by LINC01291 depletion in melanoma cells could be reversed by suppressing miR-625-5p or overexpressing IGF-1R." (PMID 33674778, 2022). "Therefore, it is safe to conclude that LINC01291 sponges miR-625-5p and subsequently upregulates IGF-1R expression in melanoma cells." (PMID 33674778, 2022). "Further, rescue experiments were implemented to assess whether miR-625-5p/IGF-1R axis contributes to the effect of LINC01291 on chemoresistance of melanoma cells to cisplatin." (PMID 33674778, 2022). "Moreover, mechanical experiments supported IGF-1R as a direct target of miR-625-5p in melanoma cells." (PMID 33674778, 2022). "Thus, LINC01291 silencing weakens the resistance of melanoma cells to cisplatin by regulating the miR-625-5p/IGF-1R axis." (PMID 33674778, 2022). "FAK and IGF1R interaction has also been shown to be critical for melanoma tumor cell growth." (PMID 34031486, 2021). "This upregulation likely occurs due to PI3K/AKT signaling activity, and targeting both E2F1 and IGF-1R may help to combat resistance in melanoma." (PMID 33807778, 2021). "Besides, ERBB1/IGF-1R/CRAF can reduce the proliferation of melanoma cells by inhibiting MAPK and/or PI3K/AKT signaling pathways." (PMID 33732282, 2021).
melanoma (continued). "A recent report on melanoma revealed that long-term mTOR kinase inhibition leads to re-activation of both pAkt S473 and pAkt T308 and that induction of IGF1R/IR-dependent PI3K activation and Akt phosphorylation is mediated by an integrin/focal adhesion kinase/IGFR-dependent process." (PMID 33273014, 2021). "Few reports discussed and evaluated IGF1R inhibition in melanoma." (PMID 33918490, 2021). "The melanoma associations of IGF1R rs2229765 and IGF1 rs1520220 were not replicable in the GENEVA dataset." (PMID 32150843, 2020). "More importantly, the associations explored in detail in this study such as the essentiality of SRF in skin and dependence of NRAS‐mutant melanoma on IGF1R and FURIN hold true in the integrated data set and with even higher confidence suggesting that these are indeed robust associations." (PMID 33073517, 2020). "Nevertheless, as the GEM cohort included multiple melanoma patients that might provide unique genetic information, the IGF1R SNP rs2229765 and IGF1 SNP rs1520220 were further analyzed in regression models." (PMID 32150843, 2020). "Notably, miR-376a directly targets IGF1R to downregulate the IGF1R signaling pathway and affects melanoma cell migration." (PMID 33321855, 2020). "In contrast, genes that were commonly downregulated in sensitive and resistant melanoma spheroids, including MMP16, IGF1R and FLOT1, are associated with malignancy, and several studies have reported that these genes are related to the aggressive behaviour of melanoma." (PMID 32613561, 2020). "Numerous results have described SERM-dependent inhibition of melanoma cell proliferation, suggesting the possible involvement of IGF1R inactivation as well as the reduction of invasion and metastasis through the inhibition of protein kinase C (PKC) downstream pathways." (PMID 32645881, 2020). "Furthermore, IGF1R and several integrin subunits isolated from melanoma cells expressing GCNT2 exhibited higher LEA lectin reactivity than controls, indicating that IGF1R and α4, β1, and β3 integrins are modified with I-branched glycans." (PMID 30135430, 2018). "We next investigated whether IGF1R itself could influence cisplatin resistance in the two melanoma cell lines." (PMID 29642855, 2018). "Taken together, our study demonstrated that miR-30a-5p could influence chemo-resistance by targeting IGF1R gene in melanoma cells, which might provide a potential target for the therapy of chemo-resistant melanoma cells." (PMID 29642855, 2018). "Analyses of two representative N-glycosylated protein families, insulin-like growth factor-1 receptor (IGF1R) and integrins, revealed that GCNT2/I-branched glycan modifications inhibited IGF-1 and ECM-mediated melanoma cell proliferation, survival, and associated downstream signaling pathways." (PMID 30135430, 2018). "Moreover, others and we have clearly demonstrated that clinical inhibition of IGF-1R would be beneficial for melanoma treatment." (PMID 29946532, 2018). "With this observation, we sought to determine whether differential GCNT2/I-branched glycan expression regulates melanoma growth and survival, in part, through IGF1R and/or through integrin-mediated pathways." (PMID 30135430, 2018). "IGF-1R signaling interfered with several crucial mechanisms involved in melanoma metastasis." (PMID 29946532, 2018). "Large amounts of preclinical, epidemiological, and clinical data clearly demonstrate a role for the IGF-1R for supporting most-if not-all cancer hallmarks associated with melanoma." (PMID 29946532, 2018). "Thus, while GCNT2/I-branched glycans decrease Gal-3-binding, we do not believe that this inhibition is responsible for mediating the observed reduction in IGF1R and integrin signaling in melanoma cells." (PMID 30135430, 2018).
melanoma (continued). "Because GCNT2 modifies polyLacNAcs, we hypothesized that GCNT2/I-branched glycans may control Gal-1- and/or Gal-3-binding in melanoma cells, thereby regulating downstream IGF1R and integrin-mediated signaling pathways." (PMID 30135430, 2018). "Hence, as a second key finding our study demonstrates that melanoma cell response to MEK1/2 inhibition with IGF-1R co-targeting critically depends on the biased or balanced conformation stabilized by the targeting agent." (PMID 29137261, 2017). "Thus, the aim of this study was to investigate the potential of balanced versus stable/transient biased IGF-1R down-regulation to enhance the response to MAPK inhibition in melanoma." (PMID 29137261, 2017). "There is evidence to suggest that co-targeting IGF-1R could enhance melanoma response to MEK inhibitors, but the role of β-arrestin-biased signaling in dual targeting systems is not known." (PMID 29137261, 2017). "Therefore, our study hints at the mechanistic rationale of combining GHR antagonism with IGF1R inhibition, as a logical treatment combination in malignant human melanoma." (PMID 28223541, 2017). "In addition, total IGF-1R expression levels were markedly reduced by IT pretreatment for 24 h in the IGF-1-stimulated melanoma cells." (PMID 27323414, 2016). "Another important question is whether miR-7 reverses the resistance to BRAFi in melanoma by modulating the expression of EGFR/IGF-1R/CRAF and the activity of their down-stream signaling pathways." (PMID 27448964, 2016). "Therefore, a further understanding of the underlying mechanisms and different roles of EGFR, IGF-1R and CRAF in BRAFi-resistant melanoma is a necessity." (PMID 27448964, 2016). "We speculate that similar regulation of IGF-1 on RUNX2 expression and activity could exist in melanoma cells, through the activation of IGF-1R and subsequent stimulation of the PI3K and/or the MAPK pathways resulting in RUNX2 positive regulation." (PMID 27102439, 2016). "Because IGF-1R, FGFR1, and EGFR have been shown to play major roles in melanoma progression through autocrine signaling, and EGF-R, PDGFRβ, and IGF-1R have been implicated in resistance mechanisms to BRAF V600E targeted therapies, we were interested in validating these results." (PMID 27102439, 2016). "The IGF1/IGF1-R nexus could be targeted for the development of more efficient anti-melanoma treatments." (PMID 27764776, 2016). "Despite their up-regulated expressions in VemR melanoma cells and definite associations with BRAFi resistance, EGFR, IGF-1R and CRAF might play different roles in development of resistance to BRAFi." (PMID 27448964, 2016). "The collective data suggested that co-inhibition of EGFR/IGF-1R/CRAF could decrease VemR A375 melanoma cell proliferation to a certain extent through the suppression of the activation of MAPK and/or PI3K/AKT signaling pathways." (PMID 27448964, 2016). "In addition, IGF-1R disruption increases the sensitivity of melanoma cells to radiotherapy and tumor necrosis factor (TNF)-related apoptosis-inducing ligand (TRAIL)-induced apoptosis." (PMID 27323414, 2016). "Therefore, as a tool to probe the relationship between IGF-1R and induction of replication-associated DNA damage, we examined responses to TMZ, a methylating agent used to treat glioblastoma multiforme and melanoma." (PMID 26497996, 2015). "In addition, recent studies demonstrated that acquired resistance to the B-RAFV600E/K inhibitor in melanoma is mediated by increased levels of IGF-1R and IRS-1, and this resistance can be effectively reversed by treatment with NT157." (PMID 26029165, 2015). "In addition, IGF-1R also stimulates cell mobility, as demonstrated by its activity in melanoma cell lines." (PMID 26329608, 2015). "IGF-1R has been shown to be up-regulated in drug resistant melanoma cell lines previously." (PMID 26029660, 2015).
melanoma (continued). "IGF-1R was expressed in all melanoma cell lines and reduced by ganetespib." (PMID 23418523, 2013). "Our results suggest that down-regulation of mir-376a and mir-376c may contribute to IGF1R over-expression and to aberrant negative regulation of this signaling pathway in melanoma, thus promoting tumorigenesis and metastasis." (PMID 22747855, 2012). "Melanomas may also over-express growth factor receptors such as insulin-like growth factor 1 receptor (IGF1-R) and Axl which can support constitutive activation of some components of the growth factor pathway." (PMID 22475322, 2012). "Moreover, a human melanoma model demonstrated that the downregulation of mir-376a and mir-376c may contribute to IGF1R (e.g., insulin-like growth factor 1 receptor) overexpression, which has been associated with insulin resistance." (PMID 41373563, 2025). "Interestingly, a study using a xenografted mice melanoma model has reported a vascular remodeling process which is mediated by the transduction signaling of the IGF1/IGF1R axis, contributing to the development of the melanoma cells which have acquired resistance to BRAF inhibition." (PMID 37174072, 2023). "Additionally, elevating the IGFBP2 expression could lead to attenuate sensitivity to MAPK signaling inhibitors, and thereby increasing BRAFV600E melanoma cell survival via triggering IGF-1R/AKT signaling pathway." (PMID 33768092, 2021). "Employing CRISPRCas9 screen targeting chromatin regulators illuminate that SIRT6 haploinsufficiency could upregulate IGFBP2 expression level as well as attenuate sensitivity to MAPKi, and thereby enhancing BRAFV600E melanoma cell survival via triggering IGF-1R/AKT signaling pathway." (PMID 33768092, 2021). "Since estrogen is able to initiate the IGF1 signaling pathway by inducing the expression of IGF1R and its downstream signaling that leads to cell proliferation, the IGF1 and IGF1R SNPs might still provide crucial information on the ER/IGF1R network in melanoma." (PMID 32150843, 2020). "Of the thirteen selected SNPs examined, IGF1 rs1520220 and IGF1R rs2229765 SNPs might appear to be significantly associated with melanoma risk in men but not in women." (PMID 32150843, 2020). "Our results indicate that IGF-1R downregulation offers an approach to increase the sensitivity of melanoma cells to MAPK inhibition, while highlighting that a good understanding of the molecular mechanisms could provide greater specificity and precision required for multi-hit personalized therapy." (PMID 29946532, 2018). "Our results indicate that IGF-1R down-regulation offers an approach to increase the sensitivity of melanoma cells to MAPK inhibition, and highlights that controlling biased signaling could provide greater specificity and precision required for multi-hit therapy." (PMID 29137261, 2017). "Additionally, decreased expression of pre-IGF1R or IGF1R was observed, suggesting that WP760-mediated IGF1R inhibition may contribute to its anti-melanoma activity." (PMID 28417283, 2017). "Initial assessment in 10 melanoma cell lines revealed that TMZ resistance correlated with MGMT expression (r = 0.79, p = 0.009), and in MGMT-proficient cell lines, with phospho-IGF-1R (r = 0.81, p = 0.038), suggesting that TMZ resistance associates with IGF-1R activation." (PMID 26497996, 2015). "Besides, MAPK-independent molecules involved in the melanoma resistance mechanism include (i) upregulation of IGF-1R; (ii) PI3K/AKT signaling through the activation of c-KIT (a RTK also known as CD117); (iii) loss of PTEN through the suppression of BIM expression." (PMID 23533766, 2013).
melanoma (continued). "Alternatively, sumoylation-mediated translocation of IGF-1R to the nucleus has recently been shown in DFB melanoma and human embryonic kidney cell lines, and the over-accumulation of SUMO conjugating enzyme (Ubc9) in the tumor nucleus is associated with elevated level of nuclear IGF-1R." (PMID 22879999, 2012). "Our data agree with other reports demonstrating that simvastatin was able to reduce IGF1R expression in PC‐3 prostate and SK‐MEL‐2 melanoma cell lines." (PMID 40874517, 2025). "Costunolide, an AKT inhibitor, has been shown to inhibit melanoma cell proliferation, and BMS-754807, an IGF1R/IR inhibitor, can also suppress tumor cell growth." (PMID 40092985, 2025). "IGFBP3-mediated IGF1R activation was first observed in erlotinib-treated PC9 cells, and a similar mechanism was also described in BRAF (V600E) melanoma cells adapting to targeted BRAF inhibition." (PMID 38473364, 2024). "Proprion one (pro-PrP) is an adaptor protein for the E3 ligase c-CBL in human melanoma, allowing it to polyubiquitinate the activated insulin-like growth factor-1 receptor (IGF-1R), thus increasing melanoma metastasis." (PMID 39130630, 2024). "Altogether, our data indicate that PTEN phosphatase activity inhibits metastasis by negatively regulating the Entpd5/IGF1R pathway through ATF6, thereby identifying novel candidate therapeutic targets for the treatment of PTEN mutant melanoma." (PMID 36824269, 2023). "Previously, we found that ABL kinases are activated by receptor tyrosine kinases such as EGFR, PDGFR, and IGF1R, and BRAF contributes to ABL1/2 activation in melanoma cells harboring BRAF-V600E." (PMID 36765910, 2023). "IGF-1R was verified as the direct target of miR-625-5p and was positively modulated by LINC01291 in melanoma cells via miR-625-5p sponging." (PMID 33674778, 2022). "S100B, VEGF (vascular endothelial growth factor), IGF-1R (the insulin-like growth factor 1 receptor), Wnt-5a, LDH (lactate dehydrogenase), and MIA (melanoma inhibitory activity) have all been shown to correlate positively with prognosis in CM." (PMID 35982458, 2022). "All these results identified a new ceRNA pathway in melanoma, which consists of LINC01291, miR-625-5p, and IGF-1R." (PMID 33674778, 2022). "SIRT6 can mediate the transcriptional regulation of IGFBP2 and therefore activate IGF-1R/AKT, which promotes the development of MAPK inhibitor resistance in melanoma." (PMID 35915188, 2022). "Overall, these data indicate that the BRAF pathway inhibitor resistant cells have elevated IGF1R at the mRNA level and melanoma patients with elevated IGF1R and INSR have a worse survival compared to patients with low levels of IGF1R." (PMID 34831014, 2021). "SOX4 seemed a likely fitting candidate, since it is not only induced during melanoma progression and promotes melanoma proliferation by AKT signaling activation, but also mediates to BRAFi in melanoma through regulation of IGF-1R." (PMID 34063443, 2021). "Then, we utilized melanoma cell lines to test the impact of miR-675-3p mimic transfection on the expression of ERG1, IGF1R, and OPCML targets." (PMID 33400243, 2021). "Examining the role of IGF1R and IR in mediating resistance to BRAF and MEK inhibitors will expand possible treatment options to aid in long-term success for BRAF-mutant melanoma patients." (PMID 34831014, 2021). "Therefore, we propose that combining dabrafenib, trametinib, and an IGF1R/IR inhibitor in patients with BRAF-mutant melanoma who have relapsed or dabrafenib and trametinib therapy regimen could be an effective strategy and warrants further investigation in the clinic." (PMID 34831014, 2021). "However, recently, it was reported that phosphatase activity of PTEN increases IGF1R expression which enhances melanoma cells resistance to vemurafenib and targeting IGF1R could be useful in melanoma patients with PTEN-positive tumors to overcome therapy resistance." (PMID 33918490, 2021).